FTO (FTO alpha-ketoglutarate dependent dioxygenase)
Diseases named in the same sentence as FTO in open-access papers (continued):
Sharing a sentence is not in itself a finding about the gene and the disease.
Obesity (continued). "Further analysis of multiple SNPs associated with obesity in FTO yielded some interesting results." (PMID 25177340, 2014). "Fourth, we systematically evaluated the impact of FTO polymorphisms on dietary behaviors (preference for a meat-based diet and salt and sweet tastes), and our findings may explain how FTO variations confer a predisposition to obesity." (PMID 25251416, 2014). "This suggests that the SNP in FTO could be utilized as a potential genetic marker of obesity risk in African populations." (PMID 24719615, 2014). "The FTO gene has been consistently associated with obesity risk." (PMID 25421534, 2014). "The question of whether the association of FTO variants and T2D is influenced by obesity or both obesity and FTO has been studied previously." (PMID 25177340, 2014). "This study confirmed the role of FTO variation on genetic susceptibility to obesity." (PMID 25251416, 2014). "The association of FTO gene SNP with obesity related parameters." (PMID 24911064, 2014). "The present study is to test whether common FTO gene SNPs are associated with obesity or related anthropometric traits in adolescents of Han Chinese." (PMID 24911064, 2014). "A preference for high-energy foods induced by FTO SNP variations, may partially explain the predisposition to obesity." (PMID 25251416, 2014). "Additionally, GWASs for obesity have clearly shown association with fat mass and obesity-associated protein (FTO)." (PMID 24719615, 2014). "The associations between common variants in the fat mass- and obesity-associated (FTO) gene and obesity-related traits may be age-dependent and may differ by sex." (PMID 24827155, 2014). "Whereas direct effect of rs9939609 on FTO function is possible, recently it has been suggested that at least for obesity the associated FTO region exerts its effect modulating expression of another relatively distant gene - IRX3 which encodes a transcription factor highly expressed in brain." (PMID 25265168, 2014). "However, findings in adult obesity/BMI GWAS of common variants in or near FTO revealed that these variants were also associated with childhood BMI and childhood obesity." (PMID 24719615, 2014). "The association between FTO rs9939609 and obesity-related traits may change from childhood to adolescence in Chinese individuals, and the association may start as early as age 12 years, especially in girls." (PMID 24827155, 2014). "The associations between FTO SNPs and obesity may be explained by their effects on dietary behaviors." (PMID 25251416, 2014). "Multiple GWAS have demonstrated further associations between variants in FTO and obesity." (PMID 25177340, 2014). "FTO demethylates N6-methyladenosine, a potential regulatory RNA modification, has recently been shown to regulate ghrelin, a hunger hormone, which predisposes to increased food intake and increases obesity." (PMID 24701352, 2014). "So our study may enrich the information about the association of FTO with obesity in adolescents of southern Han Chinese." (PMID 24911064, 2014). "Polygenic obesity association studies assessing single nucleotide polymorphisms (SNPs) have noted that many lie within the first intron of the fat mass– and obesity-associated gene (FTO) which is strongly associated with adiposity." (PMID 26217496, 2014). "The fat mass and obesity associated (FTO) gene is related to obesity and type 2 diabetes, but its function is still largely unknown." (PMID 24410832, 2014). "Recently, the fat mass and obesity associated (FTO) gene have been shown to have a relatively large effect on body mass index (BMI) and obesity-related traits in various human populations, suggesting that FTO associated with the development of fat tissue and adiposity." (PMID 26290716, 2014). "Thus, the aim of this study was to evaluate the association between five FTO SNPs, including rs9939609, rs1558902, rs8050136, rs3751812 and rs6499640 with the susceptibility to obesity in Han Chinese adolescents." (PMID 24911064, 2014).
Obesity (continued). "The FTO gene and particularly the A allele of rs9939609 polymorphism is known for association with body mass index (BMI), obesity risk, and type 2 diabetes, which has been confirmed in a Polish population as well as in a recent multiethnic study including over 170 000 individuals." (PMID 25265168, 2014). "Indeed, physical activity was recently shown to attenuate the influence of FTO variants on obesity risk." (PMID 23573268, 2013). "FTO variant associated strongly with T2D but weakly with obesity in Indians." (PMID 24102053, 2013). "The secondary aim was to examine the associations separately in normal weight and overweight individuals, challenging the question if obesity state could modify associations between the FTO variant and dietary intake." (PMID 23589710, 2013). "Therefore, the FTO association signal with obesity which was found in Mexican adults by Villalobos-Comparán and colleagues, was not confirmed in children." (PMID 23375129, 2013). "In addition, the original publication also indicated that the FTO gene variant affected T2D through an association with BMI/obesity." (PMID 23977173, 2013). "Given the mounting evidence showing a positive association between obesity and pancreatic cancer, we hypothesized that variants in the FTO gene may be associated with pancreatic cancer risk through effects on obesity or other mechanisms." (PMID 23835106, 2013). "However, the contribution of the FTO common variants to obesity is controversial in African American, Asian (Chinese Han and native Oceanic) and Hispanic populations." (PMID 23497514, 2013). "FTO is a relatively recently identified gene discovered through obesity genome-wide associated studies (GWAS) although, interestingly, the FTO gene was actually first identified in the so-called fused toes mutation in the mouse where it was found to be completely deleted." (PMID 24019958, 2013). "However, one of the strongest common genetic predictor of body mass index, the genetic variants of the FTO gene (fat mass and obesity associated gene), explain only 1% of the total heritability of obesity." (PMID 23874820, 2013). "The fat mass and obesity-associated (FTO) gene is associated with obesity in the general population, and there is evidence that single nucleotide polymorphisms (SNPs) located in intron 1 of FTO are associated with increased breast cancer risk." (PMID 24065098, 2013). "The robust association of the FTO locus with severe obesity is likely to be mediated through well-documented effects on increasing energy intake, and it is highly likely that the altered function in the FTO gene itself is mechanistically responsible for the phenotypic effects." (PMID 23950990, 2013). "The FTO A/T polymorphism (rs9939609) is a strong candidate to influence obesity-related traits." (PMID 23573268, 2013). "Thus, the aim of this study was to evaluate the association between three FTO SNPs, including rs9939609 and rs1421085, prominent in the literature, and rs1861868, yet poorly studied, with the susceptibility to obesity in a sample of Portuguese children." (PMID 23342142, 2013). "The present study is the first to test whether common FTO gene SNPs are associated with obesity or to related anthropometric traits in children of Portuguese origin." (PMID 23342142, 2013). "Interestingly, we observed a higher frequency of FTO rare non-synonymous mutations in girls of obesity as well as of lean control in our cohort." (PMID 23825611, 2013). "It has been hypothesized that the FTO gene has been associated with obesity because it can influence energy homeostasis by having a direct effect on food intake in animal models." (PMID 23497514, 2013). "The results showed association of FTO gene, rs9939609, with obesity in females (>18 years of age)." (PMID 24102053, 2013).
Obesity (continued). "Of the 15 obesity- and diabetes-associated genotypes in the FTO gene, rs9939609 was found to be positively associated with pancreatic cancer risk in persons who were overweight, whereas no increased risk was observed in persons who had a BMI of less than 25 kg/m2." (PMID 23835106, 2013). "Most studies confirmed that FTO SNPs are strongly associated with BMI and/or obesity." (PMID 23342142, 2013). "Genomewide association studies in adults have shown associations between BMI or weight and common genetic variants involved in eating behaviors, including satiety regulation and dietary intake [eg, fat mass and obesity associated (FTO) and melanocortin 4 receptor (MC4R)]." (PMID 24047917, 2013). "Difference on prevalence of FTO rare non-synonymous mutation between boys and girls with obesity." (PMID 23825611, 2013). "Since FTO controls energy homeostasis and expenditure and the FTO locus has repeatedly shown association with obesity in human studies, we tested FTO as a candidate gene in particular for milk fat yield, which represents a high amount of energy secreted during lactation." (PMID 23691044, 2013). "FTO was initially found to be associated with obesity in Caucasians." (PMID 23990951, 2013). "We assessed the association of 52 FTO polymorphisms, spanning the whole gene, with obesity and estimated the influence of these polymorphisms on anthropometric, clinical and metabolic parameters as well as inflammation and cardiovascular disease (CVD) risk biomarkers among Spanish children." (PMID 24289790, 2013). "However, all three of the FTO obesity risk variants showed an effect of increasing BMI in those born SGA, one of which was also significant in those born AGA." (PMID 23339409, 2013). "FTO was initially associated with type 2 diabetes mellitus in European descent population; however, simultaneous studies showed that the association was mediated by its effect on obesity." (PMID 24289790, 2013). "FTO minor allele increased the risk of obesity by 2.8 times (95% CI = 1.3–6.0) in females." (PMID 24102053, 2013). "Genome-wide association studies (GWAS) have revealed that the single nucleotide polymorphisms (SNPs) in the first intron of fat mass- and obesity-associated gene (FTO) are significantly associated with BMI and increased risk for obesity and it is the strongest adiposity locus identified so far." (PMID 23825611, 2013). "Note that the famous obesity-associated gene FTO was detected only via OMDR." (PMID 23819572, 2013). "Since obesity is a well established risk factor for CVD, it is more likely that the FTO gene, as the BMI/obesity related locus, might confer the risk on CVD." (PMID 23977173, 2013). "Other SNPs in FTO have been previously associated with BMI, obesity and type 2 diabetes." (PMID 24116192, 2013). "FTO harbours the strongest known obesity-susceptibility locus." (PMID 22697793, 2012). "The LP variant might have comparable or potentially even a higher effect size as the ‘fat mass and obesity associated gene (FTO)’ in some European populations." (PMID 22937140, 2012). "The fat mass and obesity associated (FTO) gene encodes a protein of unknown function in an unknown pathway." (PMID 22510482, 2012). "Further, to investigate age dependent influence of FTO variants on obesity traits, we compared the effect sizes of rs9939609 on adiposity parameters in children with that of adults from a recent and largest meta-analysis on South Asian adults (up to 17,124 adults)." (PMID 23091647, 2012). "In this unique study of a large and well standardized European cohort of children aged 2–9 years, we confirmed that the A allele of FTO rs9939609 polymorphism was associated with higher BMI and central body fat distribution and with a greater prevalence of overweight/obesity." (PMID 23155422, 2012).
Obesity (continued). "In addition, they are consistent with the findings of genetic associations between variation in FTO and obesity measures with brain volume, verbal fluency and the previous study reporting an association of the rs9939609 SNP with AD." (PMID 23251365, 2012). "Outstanding among the many genes associated with obesity is the fat mass and obesity gene (FTO)." (PMID 23284998, 2012). "Recent studies have demonstrated that polymorphisms in the Fat and Obesity-Associated (FTO) gene have strong and robust effects on obesity and obesity-related traits (such as body mass index (BMI), waist circumference, waist to hip ratio, bicondilar upper arm width and upper arm circumference)." (PMID 23251365, 2012). "FTO is the first and the most robust obesity susceptibility gene of the GWAS era." (PMID 22454631, 2012). "As FTO variants have varied longitudinal effect, association studies across the age groups are essential to comprehensively evaluate its influence in modulating the risk of obesity in a population." (PMID 23091647, 2012). "Association of FTO variants with obesity and metabolic traits in Indian children." (PMID 23091647, 2012). "Further, we explored gender differences in the effect of FTO variants on obesity measures." (PMID 23091647, 2012). "When adherence to the MedDiet was low (=<9 points), carriers of the variant allele (obesity-risk allele) had a higher risk of prevalent type 2 diabetes (OR=1.21, 95%CI: 1.03-1.40; P=0.019 for FTO and OR=1.17, 95%CI:1.01-1-36; P=0.035 for MC4R) than homozygous subjects for the major allele." (PMID 23130628, 2012). "The study presented in this paper attempts to identify the cellular consequences of FTO downregulation that may account for the influence of FTO variants on obesity." (PMID 22675562, 2012). "Finally, we reported for the first time that the A allele of FTO rs9939609 was associated to an increased incidence of overweight/obesity in children." (PMID 23155422, 2012). "However, a recent meta-analysis including 218,166 adults and 19,268 children concluded that there was a consistent statistically significant interaction between the FTO rs9939609 polymorphism and physical activity on obesity risk." (PMID 23284998, 2012). "The age related changes in lifestyle, eating behavior and exposure to environmental factors could be possible reasons for the age dependent variation in effect of FTO variants on obesity related anthropometric traits." (PMID 23091647, 2012). "Overall, multiple reports from genetics and epigenetic studies have shown compelling evidence that FTO is the strongest one of human obesity causing genes, even although the mechanisms by which FTO affect obesity are still not fully understood, the obesity risk alleles of FTO are gain of function." (PMID 22474595, 2012). "Thus, in sedentary subjects the association of the FTO polymorphisms with higher BMI or obesity risk was greater in magnitude than in active subjects." (PMID 23284998, 2012). "In the fully adjusted model (sex, age, center, diabetes, total energy intake and physical activity, each variant allele (FTO or MC4R) of the additive score increased the odds of obesity by 7% (OR = 1.07; 95%CI: 1.01–1.13) for the continuous aggregate score variable)." (PMID 23284998, 2012). "Regarding the FTO gene, a recent meta-analysis in East and South Asians, concluded that the FTO rs9939609 minor allele (or a proxy), the risk allele for obesity, increased the risk of type 2 diabetes, this association remaining statistically significant even after adjustment for BMI." (PMID 23130628, 2012). "In conclusion, we have confirmed the association of the FTO rs9939609 polymorphism with higher BMI, waist circumference and obesity even in a high cardiovascular risk population and described an additive effect of the FTO rs9939609 and the MC4R rs17782313 on these obesity-related measures." (PMID 23284998, 2012). "The association of the FTO gene with human obesity is robust in populations of European descendent." (PMID 23134754, 2012).
Obesity (continued). "Among those GWAS findings, the first obesity susceptibility locus identified was the FTO gene, which has the largest effect on obesity risk to date; each additional risk allele in FTO was shown to be associated with a 1- to 1.5-kg increase in body weight and a 20 % to 30 % increase in obesity risk." (PMID 24392269, 2012). "Experimental animal studies provide direct functional evidence that FTO underlies obesity." (PMID 21347432, 2011). "Likewise, the fat mass and obesity associated (FTO) locus, which has the strongest known association with obesity in Europeans, shows a complex and inconsistent pattern in African-origin populations." (PMID 21573225, 2011). "Further study of additional genetic correlates of body weight will assist in clarifying whether the FTO relation to endometrial cancer risk is unique among ‘obesity-associated’ genes." (PMID 21347432, 2011). "FTO gene has been consistently identified to be associated with obesity phenotypes." (PMID 22125610, 2011). "We, therefore, aimed to evaluate FTO expression during human adipocyte differentiation to assess whether the association of FTO with obesity may be directly related to adipogenesis." (PMID 21687707, 2011). "Variants in the FTO gene have been unequivocally and robustly associated with obesity risk." (PMID 21687707, 2011). "This suggests that the genomic region of FTO might harbor multiple variants that influence susceptibility to develop obesity or related traits and indicate the importance of studying a broader range of SNPs in a wider region." (PMID 21637715, 2011). "In total, 733 SNPs located in the FTO gene were genotyped in order to examine whether rs9939609 alone or the other SNPs, or their combinations, are linked to obesity-related measures in elderly humans." (PMID 21637715, 2011). "Common variants in the FTO gene are linked to obesity in childhood and young adulthood." (PMID 21637715, 2011). "Other studies, however, were unable to replicate this interaction, leaving it unresolved whether physical activity (PA) can reduce FTO’s effect on obesity risk, and if so, to what extent." (PMID 22069379, 2011). "This meta-analysis suggests that FTO may represent a low-penetrance susceptible gene for obesity risk." (PMID 21651756, 2011). "Intriguingly, SNPs in regions beyond the first intron have also been associated with obesity-related traits, indicating that specific regions in the very large FTO gene spanning more than 400 kb may be differentially associated with obesity-related phenotypes." (PMID 21637715, 2011). "However, in 2007, the intron 1 of the fat mass and obesity associated (FTO) gene was identified as the first robust obesity-susceptibility locus in genome-wide association studies." (PMID 22069379, 2011). "Interestingly, one study reported differential associations of the FTO gene for Whites and African-Americans with respect to obesity." (PMID 21526213, 2011). "The pathogenesis of obesity is reportedly related to variations in the fat mass and an obesity-associated gene (FTO); however, as the number of reports increases, particularly with respect to varying ethnicities, there is a need to determine more precisely the effect sizes in each ethnic group." (PMID 21651756, 2011). "After a 1-month weight control containing low-calorie diet, the carriers of the obesity-risk alleles might undergo significant changes in FTO mRNA expression within the hypothalamic nuclei." (PMID 19822564, 2011). "The FTO gene harbors the strongest known susceptibility locus for obesity." (PMID 22069379, 2011). "So far, it is unclear how FTO increases the susceptibility to develop overweight and obesity and whether this association is of correlative or causative origin." (PMID 21637715, 2011).